VDR (vitamin D receptor)
Diseases named in the same sentence as VDR in open-access papers (continued):
Sharing a sentence is not in itself a finding about the gene and the disease.
neuroblastoma (9 papers, 2016 to 2025). Neuroblastoma (NB) is the most common solid, extracranial childhood tumor. "Calcipotriol, while reducing neuroblastoma cell proliferation and survival through vitamin D receptor signaling, also regulates cell migration by inducing RASSF2-dependent muting of the Hippo signaling pathway and Hippo pathway effectors (e.g., YAP and TAZ)." (PMID 38249515, 2023). "In the case of neuroblastoma, it was observed that mature ganglion cells in the tumor showed mainly significant VDR expression." (PMID 35884356, 2022). "A respected study of the human neuroblastoma cell line identified the exact signaling pathway through which VDR exerts its antiproliferative effect." (PMID 35884356, 2022). "The presence of vitamin D receptor (VDR) in neuroblastoma cell lines, along with its quantities and the impact of the active vitamin D3 metabolite on VDR signalling, have all been linked to the mechanism of action of vitamin D3 in neuroblastoma cell lines." (PMID 40531759, 2025). "This comes as a relative surprise since it has been reported that either the cotransfection of VDR or a calcitriol treatment reduces, in a dose dependent manner, APP transcription in neuroblastoma cells." (PMID 26932723, 2016). "Immunoblottingshows that VDR and MYCN are expressed in neuroblastoma cell-lines." (PMID 35404047, 2022).
non-alcoholic fatty liver disease (9 papers, 2020 to 2024). "SNPs of VDR are not only associated with incidence risk or prognosis of cancer, but are also associated with other diseases, such as nonalcoholic fatty liver disease." (PMID 35637613, 2023). "Our recent study showed that VDR rs2228530 genetic alleles with AA and AG may be associated with the development of non-alcoholic fatty liver disease after LDLT." (PMID 35629892, 2022). "It has been demonstrated that vitamin D receptor (VDR), a key gene in the metabolism of vitamin D (VD), may affect the development of Non-alcoholic fatty liver disease (NAFLD) by regulating VD level and its biological effects." (PMID 34421816, 2021).
parathyroid adenomas (9 papers, 2014 to 2025). "VDR polymorphism TaqI was correlated with parathyroid adenoma development, while VDR stained positive in immunohistochemical study." (PMID 40186735, 2025). "The results of our genetic study demonstrated VDR polymorphism TaqI as a cofounding factor for parathyroid adenoma formation." (PMID 40186735, 2025). "Regarding genetic study, only VDR gene polymorphism TaqI TC and TT genotypes were correlated to sporadic parathyroid adenoma development concerning additive and recessive models." (PMID 40186735, 2025). "Vitamin D Receptor was found to be linked to sporadic parathyroid adenoma development by distinct genetic and immunohistochemical studies." (PMID 40186735, 2025). "Reduced expressions of CaSR and vitamin D (1,25- dihydroxyvitamin D3) receptor (VDR) have been implicated in aberrant calcium signaling in sporadic parathyroid adenomas indicating their mechanistic roles in parathyroid tumorigenesis." (PMID 35681135, 2022). "These alternative modes of PTH hypersecretion revealed distinct actions of the CaSR and the VDR that may underlie the divergent secretory patterns seen in different types of parathyroid adenomas." (PMID 40492090, 2025). "Concluding, this study confirms the contribution of vitamin D receptor in sporadic parathyroid adenoma development in Greek population." (PMID 40186735, 2025). "Specifically, the aim of our pilot study is to evaluate Vitamin D receptor gene expression pattern in parathyroid adenoma patients in Greek population." (PMID 40186735, 2025). "Our study suggests VDR as a major contributor to sporadic parathyroid adenoma formation in Greek population." (PMID 40186735, 2025). "When the overall rate of positive staining was evaluated, including cytoplasmic, nuclear and membranous types, it was found 78.5%, proposing a potential novel immunohistochemical pattern for VDR expression in parathyroid adenoma cells." (PMID 40186735, 2025). "The aim of this study is to evaluate the immunohistochemical staining of ANXA2, MED12, MAPK1 and VDR in parathyroid adenoma tissue." (PMID 39064529, 2024). "In parathyroid adenoma, it has already been found that VDR expression is decreased and thus in oxyphil cells." (PMID 39064529, 2024). "The aim of our study is to evaluate the quantitative expression of four gene proteins (ANXA2, MED12, MAPK1 and VDR) by immunohistochemical analysis in tissue samples of parathyroid adenoma, as well as their qualitative characteristics." (PMID 39064529, 2024). "Immunohistochemical analysis of ANXA2, MED12, MAPK1 and VDR proteins in sporadic parathyroid adenoma confirmed their expression in parathyroid cells." (PMID 39064529, 2024). "ANXA2, MED12, MAPK1 and VDR proved to have a positive staining in the immunohistochemical study of sporadic parathyroid adenomas in varying intensity and allocation percentages." (PMID 39064529, 2024). "VDR expression has been found downregulated in parathyroid adenomas." (PMID 40186735, 2025). "The aim of this study is to evaluate Vitamin D receptor expression in sporadic parathyroid adenoma." (PMID 40186735, 2025). "In our study, VDR appeared to be expressed in parathyroid adenoma." (PMID 39064529, 2024). "For example, analysis of parathyroid adenomas showed no mutations in the coding regions of the VDR gene." (PMID 24626468, 2014). "Second, transcriptomic analyses of parathyroid adenomas show an inverse relationship between APP and VDR RNA expression." (PMID 40492090, 2025). "Materials and Methods: Fifty-one parathyroid adenomas were analyzed for ANXA2, MED12, MAPK1 and VDR expressions." (PMID 39064529, 2024). "VDR and PTH gene expression in parathyroid adenomas ranges from very low to high compared to normal tissue where PTH and VDR are highly expressed." (PMID 37223014, 2023).
parathyroid adenomas (continued). "studies in rats, CaSR, VDR, and RET gene evolvement in parathyroid adenoma has not been confirmed, although these are involved in hereditary disease and play significant role in parathyroid gland biological processes." (PMID 37223014, 2023).
periodontal disease (9 papers, 2010 to 2024). "We analyzed the genetic variants of VDR because it is now recognized that these polymorphisms play a certain role in the susceptibility to periodontal disease." (PMID 39451399, 2024). "Based on these findings, a pilot study was performed analyzing the VDR polymorphisms FokI, BsmI, ApaI, and TaqI on a selected Italian population composed of fifty patients with periodontal disease and forty-one healthy controls." (PMID 35740958, 2022). "As it can be observed, there is inconsistency regarding the association of the various VDR gene polymorphisms and periodontal disease." (PMID 32238981, 2020). "Since alveolar bone resoption is a major characteristic of periodontal disease, it is plausible that mediators of bone metabolism like the vitamin D receptor (VDR) and its' genetic polymorphisms play a role in CP susceptibility." (PMID 20339487, 2010). "In conclusion, our findings suggest the involvement of the VDR gene BsmI and TaqI polymorphisms in periodontal disease, while FokI and BsmI may be important in determining an increased presence of periodontopathogens." (PMID 35740958, 2022). "This SNP was associated with a variety of conditions and phenotypes (NCBI), including periodontal disease and molar incisor hypomineralization, and it was also suggested that it could be associated with VDR mRNA expression in PDL cells." (PMID 36555589, 2022). "We selected three common SNPs in the VDR gene, known as FokI, BgII and ApaI, which have been widely explored in the literature and are associated with different phenotypes/conditions including periodontal disease and external apical root resorption during orthodontic treatment." (PMID 34362362, 2021). "Vitamin D receptor (VDR) polymorphisms appear to be related to the presence and level of periodontal pathogens, qualifying the genetic predisposition to develop periodontal disease." (PMID 39451399, 2024). "A number of candidate gene studies showed that IL1A, IL1B, IL4, IL6, IL10, TNFA, FcγR, VDR, TLR2, TLR4, and MMP1 were the main genes associated with periodontal disease." (PMID 36294882, 2022). "Gene polymorphisms have been investigated as possible markers of increased susceptibility to periodontal diseases: IL-1, IL-4, IL-10; TNF-α; Fcγ receptor; human leukocyte antigen; vitamin D receptor; and N-formyl peptide receptor." (PMID 20170537, 2010). "SNPs can influence the expression and/or functions of the VDR and have been explored in complex traits, including oral phenotypes, such as periodontal disease, external apical root resorption as a sequela of orthodontic treatment, developmental dental alterations, and malocclusion." (PMID 36555589, 2022). "Several studies have shown a relationship between periodontal disease and genetic factors, including polymorphisms in interleukin (IL)-1, interferon-γ, IL-6, matrix metalloproteinase (MMP)-9, tissue inhibitor of MMP-2, vitamin D receptor, IL-1α, and IL-1β." (PMID 23050158, 2012). "Finally, no definite conclusion on the effects of VDR polymorphisms and periodontal disease can be drawn, as shown by the conflicting outcomes of the studies identified." (PMID 32238981, 2020). "However, despite the large number of studies on VDR polymorphisms, it has not yet been clearly established whether any of them can influence the risk of periodontal disease, and in many cases, the results are contradictory and controversial." (PMID 35740958, 2022).
postmenopausal osteoporosis (9 papers, 2015 to 2024). Metabolic disorder associated with fractures of the femoral neck, vertebrae, and distal forearm. "This study aimed to determine the influence of VDR gene variants on anti-osteoporotic one-year treatment with denosumab in 63 Polish women with postmenopausal osteoporosis." (PMID 36714573, 2022). "A recent meta-analysis shows that VDR BsmI is associated with an increased risk of postmenopausal osteoporosis in Asians, while in Caucasians seem to be unrelated, which is contrary to the results of two previously published studies." (PMID 33238893, 2020). "Results on the relationships between vitamin D receptor (VDR) gene polymorphisms and postmenopausal osteoporosis susceptibility and BMD are conflicting." (PMID 31616375, 2019). "This study is focused on association of VDR gene variants with susceptibility to postmenopausal osteoporosis (PMO)." (PMID 29922235, 2018). "Pharmacogenetic studies raise the question of whether polymorphism of the VDR gene influences denosumab treatment efficacy in women with postmenopausal osteoporosis." (PMID 36714573, 2022). "This study aimed to determine the influence of VDR gene variation on anti-osteoporotic one-year treatment with denosumab in 63 Polish women with postmenopausal osteoporosis." (PMID 36714573, 2022). "Focusing on studies from recent years regarding the impact of the BsmI variant of the VDR gene in women with postmenopausal osteoporosis, regardless of the treatment, the results are discrepant." (PMID 36714573, 2022). "For example, in a survey of the Thai population, VDR BsmI polymorphism did not seem to be associated with the risk of postmenopausal osteoporosis." (PMID 33238893, 2020). "Through our meta-analysis, it has been found that the VDR Bsml gene polymorphism generally seems not to be a susceptibility gene for postmenopausal osteoporosis." (PMID 33238893, 2020). "The present meta-analysis suggests that VDR BsmI genotype is associated with increased risk of postmenopausal osteoporosis in Caucasians but not in Asians." (PMID 33238893, 2020). "In conclusion, our study believes that VDR BsmI polymorphism and postmenopausal osteoporosis are genetically linked in Caucasians, but not in Asians." (PMID 33238893, 2020). "VDR dysfunction might substantially contribute to development of postmenopausal osteoporosis (PMO)." (PMID 29922235, 2018).
primary biliary cirrhosis (9 papers, 2012 to 2024). "Multiple studies demonstrated a correlation between VDR polymorphisms and susceptibility to primary biliary cholangitis in different ethnic groups." (PMID 36012285, 2022). "On the basis of the results of this study, we validated our previous conclusion that these variants of the VDR gene may prompt more severe liver injury and a worse course of primary biliary cholangitis." (PMID 32727130, 2020). "In the context of biliary tract cancer and autoimmune diseases, VDR polymorphisms have been associated with an elevated risk of GBC and primary biliary cirrhosis." (PMID 39683528, 2024). "Kempinska‐Podhorodecka et al20 showed that expression of the VDR gene in PBMCs of patients with primary biliary cirrhosis and primary sclerosing cholangitis is decreased." (PMID 31709782, 2019). "In light of the presented findings, we conclude that inadequate VDR signaling in primary biliary cholangitis with subsequent, miRNA155-modulated SOCS1 expression may lead to the insufficient negative feedback regulation of cytokine signaling." (PMID 28146070, 2017). "Additionally, reduced VDR expression has been observed in GBC samples compared to benign conditions, and VDD has been associated with an incomplete response to ursodeoxycholic acid (UDCA) in primary biliary cirrhosis patients." (PMID 39683528, 2024).
acute respiratory distress syndrome (8 papers, 2021 to 2024). Progressive and life-threatening pulmonary distress in the absence of an underlying pulmonary condition, usually following major trauma or surgery. "The proposition has been put forward that activation of VDR may have the capacity to decrease the likelihood of acute respiratory distress syndrome (ARDS), cardiac complications, coagulopathy, and mortality in patients with COVID-1910–14." (PMID 38902265, 2024). "The activation of the signaling pathway of the VDR seems to generate positive effects in Acute Respiratory Distress Syndrome (ARDS), inducing a mitigation of the so-called “cytokine storm”, thus playing an important immuno-modulatory and anti-inflammatory role." (PMID 35276834, 2022). "Discrepancies with the data in VDR−/− mice might be related to differences in infectious doses where pneumonia or an acute respiratory distress syndrome is induced rather than a lower respiratory tract infection." (PMID 35236342, 2022).
AIDS (8 papers, 2012 to 2021). A syndrome resulting from the acquired deficiency of cellular immunity caused by the human immunodeficiency virus (HIV). "The VDR variant rs1544410_AA was also associated with the progression to AIDS and resistance to HIV-1." (PMID 32235600, 2020). "In conclusion, the VDR rs2228570 T allele was related to a lower AIDS progression rate in European ART-naïve HIV-infected patients." (PMID 30841566, 2019). "Our most significant finding was that, HIV-infected patients carrying the VDR rs2228570 T allele, had lower odds of progression to AIDS." (PMID 30841566, 2019). "Afterwards, we evaluated the association of rs16846876 and rs12512631 polymorphisms with AIDS progression by GLMs adjusted by age, gender, risk category, and VDR rs2228570 SNP." (PMID 31640710, 2019). "We explored the genetic association between VDR SNPs (rs11568820, rs1544410, rs2228570, rs4516035, and rs7975232) and the three clinical patterns of AIDS progression (LTNP, MP, and RP) by univariate analysis." (PMID 30841566, 2019). "Furthermore, HIV+ subjects with vitamin D receptor variants showed a significantly increased risk of progression to AIDS." (PMID 33066266, 2020). "Within all HIV patients, the presence of T allele at VDR rs2228570 SNP was protective against AIDS progression (ordinal outcome) under additive (adjusted odds ratio (aOR) = 0.75; p = 0.009), dominant (aOR = 0.69; p = 0.015), and codominant (aOR = 0.56; p = 0.017) inheritance models." (PMID 30841566, 2019). "The VDR variants observed were TaqI (rs731236), in 30 patients with MS (85.7%), 11 individuals with other AIDs (84.6%), and in 35 unaffected individuals (76.1%); and FokI (rs2228570) in 30 patients with MS (85.7%), 12 individuals with other AIDs (85.7%), and in 41 unaffected individuals (89.1%)." (PMID 30900415, 2019). "VDR diplotypes in 5′ untranslated region (UTR) and 3′UTR locus combinations were associated with the pathogenesis of AIDS." (PMID 32235600, 2020). "In this study, we analyzed the association among single nucleotide polymorphisms (SNPs) in the vitamin D receptor (VDR) gene, with clinical patterns of AIDS progression in antiretroviral treatment (ART)-naïve HIV-infected patients." (PMID 30841566, 2019). "There is scarce information about VDR SNPs on the progression to AIDS in naïve HIV-infected patients, and these studies were performed with lower sample sizes." (PMID 30841566, 2019). "Despite this, we do not necessarily think that this association between VDR rs2228570 SNP, and the clinical patterns of AIDS progression, could be a false positive." (PMID 30841566, 2019). "Notably, the VDR-BB genotype was correlated with more rapid progression to both CD4 counts <200 cells/uL and acquired immunodeficiency syndrome (AIDS)." (PMID 24278668, 2012). "Thus, since VDR SNPs have been associated with a large number of immune-mediated diseases, we hypothesized that these SNPs could play an important role in the clinical progression of HIV-infected patients, and could be associated with clinical patterns of AIDS progression." (PMID 30841566, 2019).
anemia (8 papers, 2012 to 2025). A reduction in the number of red blood cells, the amount of hemoglobin, and/or the volume of packed red blood cells. "Recent studies have indicated that vitamin D/VDR can downregulate the expression of FOXO1 in diabetic patients, inhibiting iron-deficiency anemia in pancreatic β-cells." (PMID 38978780, 2024). "This study found a significant moderate correlation between anemia with VDR and HMGB1 in HIV infection." (PMID 33664952, 2021). "There were moderate correlation between anemia with VDR and HMGB1 (r = 0,518, r = −0,518; p < 0,001)." (PMID 33664952, 2021). "Studies suggest that vitamin D may reduce anemia by directly stimulating erythroid precursors, as the vitamin D receptor (VDR) is present in bone marrow at concentrations 100 times higher than in plasma." (PMID 39727427, 2024). "However, there was no previous study that reported the association between anemia with VDR and HMGB1 in HIV infection." (PMID 33664952, 2021).
bronchiolitis (8 papers, 2013 to 2022). Inflammation of the bronchioles characterized by swelling of the bronchioles and mucus accumulation. "Moreover a significant relationship between the severity of bronchiolitis and vitamin D receptor polymorphism as well as vit D levels in patients was shown." (PMID 35692038, 2022). "Meta-analysis has shown increased odds (OR 1.52, p = 0.007) for hospitalization for respiratory syncytial virus (RSV) bronchiolitis in infants who possess a minor allele for a VDR polymorphism (Fok1-f rs2228570) that lowers the transcriptional activity of the VDR." (PMID 33489300, 2020). "Moreover, genetic polymorphisms in VDR have been associated with hospitalization for acute bronchiolitis in infancy." (PMID 26521023, 2015). "This study also used retroviral transduction to overexpress the common M4 VDR variant, or the M1 FokI VDR variant, which has been associated with severe RSV bronchiolitis." (PMID 26035247, 2015).